IL18 (interleukin 18)
Diseases named in the same sentence as IL18 in open-access papers (continued):
Sharing a sentence is not in itself a finding about the gene and the disease.
infection (continued). "IL-1β and IL-18 levels were reduced in the lungs of Gsdmd−/− mice after infection but levels of these cytokines were not entirely dependent on GSDMD, despite the canonical role of GSDMD in IL-1β and IL-18 release." (PMID 38553499, 2024). "However, the addition of IL-1β, and/or IL-18 to macrophages at the time of infection did not suppress Legionella replication in Ipaf knockout macrophages, indicating that caspase-1 activation is critical for the clearance of the bacterium independently of the activity of IL-1β and IL-18." (PMID 39625520, 2024). "Next, IL-1β and IL-18 released in the supernatant of untreated or HSV-1-infected cells expressing, or not, the ICP27 gene were quantified at 10 h post-infection by performing an ELISA assay." (PMID 38731826, 2024). "Similarly, low production of virions from reactivated reservoir cells could result in abortive infection in presence of ART, leading to activation of inflammasome and proinflammatory caspases responsible for release of proinflammatory cytokines (IL-1β and IL-18)." (PMID 37953818, 2023). "In this infection condition, activation of iNKT and MAIT cells, but not γδ-T cells, was correlated with both IL-18 secretion and disease severity." (PMID 37228593, 2023). "Infection of PMA-matured THP-1 cells by both vaccine and WT MeV was sufficient to trigger inflammasome activation for production of IL-1β and IL-18 independent of extracellular virus production." (PMID 36851476, 2023). "We found that SubAB reduced activation of the STEC O113:H21 infection-induced non-canonical NLRP3 inflammasome and interleukin (IL)-1β and IL-18 production in murine macrophages." (PMID 35345462, 2022). "Within the first 5 days of infection, the absolute numbers of ILC2 did not significantly change in the dermis, which is in line with the unaltered expression of cytokines activating (IL-18, IL-25, IL-33, TSLP) or inhibiting ILC2 (IL-27, IFN-γ)." (PMID 35894051, 2022). "In contrast, infection of wild-type BMDM with SCHU S4 resulted in no measurable levels of IL-1β and in the presence of IFN-γ, low levels of IL-18, whereas no IL-18 was secreted in the absence of IFN-γ." (PMID 35004352, 2021). "In human macrophages, gene expression levels for IL‐1β, IL‐18, and TNF‐α from WT infections remained low and were never two‐fold higher than uninfected macrophages." (PMID 33970545, 2021). "The levels of IL-18 and IL-1ß were significantly increased in the infection group compared with the normal control group, but IFKOS showed no obvious inhibitory effect on the elevated levels of IL-18 and IL-1ß." (PMID 30305831, 2018). "IL-18 was secreted at low levels by CMT-93 cells, but this response was not affected by infection or P2X7R inhibition." (PMID 27559003, 2017). "Secretion of IL18, but not IL1B was induced by C. albicans, which is consistent with the pro-inflammatory nature of the infection." (PMID 28369145, 2017). "We found a significant increased production of IL-1α and IL-1β, but not IL-18, and of the cleaved fragment of procaspase-1 in the lungs of Cftr–/– than C57BL/6 mice during either infection." (PMID 26972847, 2016). "Some analytes were not significantly increased with infection but were significantly reduced by treatment with the anti-IL-7Rα M595: MCP-1, MCP-3, MDC, MIP-1α, MIP3β, GCP-2, IL-18, Tissue Factor, and TPO." (PMID 23057802, 2012). "More important, although BCG vaccination or IL-12+IL-18 treatment had no impact on other ILC subsets, higher numbers of ILC1-like cells were detected at 14 days post-infection, a time when IFN-γ -producing ILC1-like cells were virtually absent from non-vaccinated mice." (PMID 35443177, 2022). "Unlike immune cells and epithelial sources, neurons expressing IL-18 non-redundantly instruct cupped cells to program AMP production, reinforce the sterile intra-mucosal barrier during homeostasis, and help kill intestinal pathogens during infection." (PMID 35216425, 2022).
infection (continued). "Instead, infection with the virulent 22653/14 ASFV did not alter any surface marker expression and did not trigger the release of either IFNβ, anti-inflammatory IL-10, proinflammatory (IL-1β, IL-6, IL-8, TNF-α), and pro-Th1 (IL-12, IL-18) cytokines." (PMID 35215216, 2022). "In contrast, moM1 infection with virulent 22653/14 ASFV did not induce the release of either proinflammatory (IL-1α, IL-1β, IL-6, TNF-α) or anti-inflammatory (IL-10) or pro-Th1 (IL-12, IL-18) cytokines." (PMID 35215216, 2022). "In contrast, IL-22 injection into Il-18−/− mice failed to promote mucin secretion, which is reminiscent of the results that IL-22 injection also failed to restore Paneth cell or IFNγ response in Il-18−/− mice during AIEC infection." (PMID 35169117, 2022). "Additionally, while our results demonstrate an important role for IL-18, the reduction in disease severity was not as profound as therapeutic IFNAR blockade in our HSV-2 model of infection." (PMID 34047696, 2021). "However, replication of the virus does continue to lead to some downregulation of inflammasome activation in IFNγ-treated macrophages because HSV-1/UV led to increased IL-18 production versus HSV-1, albeit not until 24 hours post infection." (PMID 32101570, 2020). "The different level of inflammasome activation in response to distinct Mtb strains has also been observed in the murine model of infection, showing that MP287/03 is a poor inducer of IL-1ß both in vivo and in vitro compared to H37Rv or Beijing; IL-18 was not, however, evaluated in these models." (PMID 33193317, 2020). "Regardless of the infection, TNF-α, IL-15, IL-18, and CCL-5 were absent or barely detected." (PMID 30420629, 2018). "Finally, we showed using a murine CBM model that F. pedrosoi elicits a NLRP3-regulated IL-1β and interleukin-18 release in vivo, but without NLRP3 inflammasome activation interfering in the course of the experimental infection." (PMID 29209318, 2017). "IL-18 was initially shown to synergize with IL-12 for IFN-γ production by Th1 cells in vitro, but its essential role in promoting Th1 responses to infection was not always confirmed in the context of in vivo infection." (PMID 28895840, 2017). "Whereas circulating IL-18 levels were low and showed a decreasing trend without difference between WT and NLRP3−/− mice, levels of IL-1β progressively increased in T. crassiceps-infected WT mice reaching a significant increase in week 8 of infection as compared to NLRP3−/− mice." (PMID 38842647, 2024). "These cells exhibit innate characteristics during inflammation and infection, such as rapid activation kinetics without prior pathogen exposure, and the capacity for TCR-independent activation by inflammatory cytokines such as IL-12, IL-18, and type I interferons." (PMID 36911660, 2023). "While IL-18 expression did not change at any time point (data not shown), a robust up-regulation was detected in the expressions of IL-1β, -6, -8, and TNF-α at days 2 and 3 after infection with both MOI-1 and -5 of WNV, which coincided with increase in cell toxicity following WNV infection." (PMID 21034511, 2010). "Notably, infection with L. infantum did lead to an upregulation of IFN-γ mRNA in partially (70%) or highly purified splenic NK cells (>99.9%) and the levels of IFN-γ mRNA were comparable in WT and IL-18−/− mice (data not shown)." (PMID 20213736, 2010).
cancer (416 papers, 2004 to 2026). A tumor composed of atypical neoplastic, often pleomorphic cells that invade other tissues. "Both preclinical models and human cancer studies have linked IFNγ-related signatures, including IL-18, to improved prognosis." (PMID 41087719, 2025). "The NLRP3 inflammasome, which processes pro-inflammatory cytokines IL-1β and IL-18, has been implicated in cancer-related inflammation, and preliminary data indicate that dietary polyphenols can inhibit inflammasome activation." (PMID 41226270, 2025). "The latest study showed that Casp1‐/‐ and Asc‐/‐ and Il‐18‐/‐ and Il‐18R1‐/‐ mice also showed increased susceptibility to cancer after AOM/DSS exposure." (PMID 40671401, 2025). "This dual modulation of IL-1β suppression and IL-18 activation highlights unique advantage of plant-derived EVs in targeting cancer-associated inflammation." (PMID 40604924, 2025). "Interleukin-18 (IL-18) is a proinflammatory cytokine implicated in immune response regulation and the pathogenesis of diverse diseases, including cancer and inflammation." (PMID 38254861, 2024). "One mutant allele in IL-18 G-137C polymorphism increased the chance of cancer (OR = 5.583, 95% CI = 3.04–10.22, P < 0.001) and two mutant alleles increased more (OR = 9.571, 95% CI = 3.10–29.46, P < 0.001)." (PMID 39359425, 2024). "One mutant allele in IL-18 C-607A polymorphism increased the chance of cancer (OR = 5.359, 95% CI = 2.95–9.70, P < 0.001) and two mutant alleles increased more (OR = 7.083, 95% CI = 2.61–19.15, P < 0.001)." (PMID 39359425, 2024). "One mutant allele in IL-18 C607A polymorphism (CA) increased the chance of cancer (OR = 5.359, 95% CI = 2.95–9.70) and two mutant alleles (AA) increased more (OR = 7.083, 95% CI = 2.61–19.15) (P < 0.001)." (PMID 39359425, 2024). "One mutant allele in IL-18 G-137C polymorphism (CG) increased the chance of cancer (OR = 5.583, 95% CI = 3.04–10.22) and two mutant alleles (CC) increased more (OR = 9.571, 95% CI = 3.10–29.46)." (PMID 39359425, 2024). "For instance, researchers are currently exploring and publishing papers on the role of IL‐18 in cancer immunotherapy and its association with the pathogenesis of cardiovascular diseases." (PMID 39188114, 2024). "The protective role of IL-18 in CRC is an interesting finding since IL-18 expression has been studied in various cancers and is generally linked with poor prognosis." (PMID 38031951, 2023). "The multivariable Cox proportional hazards regression model implied that the high IL-18 expression and positive carcinoma cell embolus were both independent risk factors for unfavorable prognosis." (PMID 38031068, 2023). "Kaplan–Meier survival analysis revealed that high IL-18 expression in the immune-stromal cells and the positive carcinoma cell embolus were both associated with poor survival (P < 0.05)." (PMID 38031068, 2023). "Several genes and gene products were identified as targets of miR-223, including NLRP3, IL18, IL1β, DNA methyltransferase 1, and checkpoint kinase-1, signifying its potential use as a cancer-specific diagnostic biomarker and therapy." (PMID 35205115, 2022). "Neutrophils and platelets have been implicated in cancer immune-escape and progression trough cytokines productions (e.g., IL-18, VEGF, and PDGF)." (PMID 35008350, 2021). "Several studies have demonstrated the association between various types of cancer and polymorphisms on the IL-18 gene, despite the chronic inflammatory status of cancer patients." (PMID 33507690, 2021). "Constitutive activation of caspase-1 in EBV-associated cancer facilitates viral genome persistence and immune evasion via cleavage of the pro-forms of IL-1β and IL-18." (PMID 33918087, 2021). "Pin1 promoted cancer progression by increasing IL‐18 expression, while Pin1 knockdown impaired IL‐18‐associated proliferation and metastasis." (PMID 32347623, 2020).
cancer (continued). "In the case of IL-18, a significant (p <0.001) increase of 2.08 (CI% 95 1.06-3.99) was noted which shows there is a risk of the cancer progressing from HSIL if the IL-18 expression decreases." (PMID 31554368, 2019). "The results showed that an increase in the risk of progression of pre-neoplastic lesions to cancer was between 2.5 and 2.08 times higher in women with lower IL-1β and IL-18 expression, respectively." (PMID 31554368, 2019). "Most of the previous genomic studies on human IL-18 were devoted to examining the association of IL-18 -607 and -137 polymorphisms with various types of cancer." (PMID 30925760, 2019). "Cytokines such as tumor necrosis factor-α, interleukin-1, IL-6, and IL-18; oxygen free radicals; and nitrogen-based biological effectors have all been implicated in promoting cancer cell growth." (PMID 28284210, 2017). "A pooled analysis found that both IL-18-607(C/A) and-137(G/C) polymorphisms were associated with significant increase in cancer risk." (PMID 29312552, 2017). "Clinical studies have provided evidence that the measurement of IL-1β and IL-18 correlates with the risk of carcinoma and the prognosis of established cancer including prostate." (PMID 28663562, 2017). "IL-1β and IL-18 are considered to be indicators of an increased risk of carcinoma and poor prognoses in multiple cancers." (PMID 28974683, 2017). "The mechanisms by which hUMSCs/IL-18 caused the growth attenuation of cancer cells were determined by cell cycle analysis with flow cytometry." (PMID 25780408, 2015). "Consistent with the theory that Th1 cells are associated with immunity to cancer, the administration of IL-18 can result in notable antitumor effects." (PMID 25780408, 2015). "Myeloid cells, including immature myeloid cells, neutrophils and macrophages, represent one of the most frequent immune cells associated with cancer and a cellular source for inflammasome activation and secretion of IL-1β and IL-18." (PMID 24474192, 2014). "During sub-group analyses, we found that the source of controls also affected the association between -607C/A polymorphisms in IL-18 gene promoter and cancer risk." (PMID 24130810, 2013). "Similar to IBD, polymorphisms in the IL-18 promoter region are also strongly associated to GI-related cancers." (PMID 23847622, 2013). "The present meta-analysis, which included 4100 cancer cases and 4327 controls from 21 publications with 22 case-control studies, explored the relationship between -607C/A polymorphisms in IL-18 gene promoter and cancer risk." (PMID 24130810, 2013). "Several observational studies have investigated the association between -607 C/A polymorphism of IL-18 gene promoter and cancer risk; however, the results were inconsistent." (PMID 24130810, 2013). "Overall, a significant association exists between -607C/A polymorphisms in IL-18 gene promoter and cancer risk." (PMID 24130810, 2013). "Several observational studies have investigated the association between -607 C/A polymorphism of IL-18 gene and cancer risk; however, the results were inconsistent." (PMID 24130810, 2013). "So we found that cancer types greatly affected the association between IL-18 gene promoter −607 C>A polymorphism and cancer risk, but ethnicities failed." (PMID 24066061, 2013). "We assessed the strength of the association of IL-18 gene promoter −607 C>A and −137G>C polymorphisms with cancer risk and performed sub-group analyses by cancer types, ethnicities, source of controls and sample size." (PMID 24066061, 2013). "Futher, the number of studies which investigated the association between -607C/A polymorphisms in IL-18 gene promoter and risk of different types of cancer was too small(≤3), which limited us to detect stable effects on different cancer types." (PMID 24130810, 2013).
cancer (continued). "Significant association between -607C/A polymorphism in IL-18 gene promoter and cancer risk was observed (CA vs CC:OR =1.221, 95% CI: 1.096, 1.360; Pheterogeneity=0.219; AA/CA vs. CC:OR =1.203, 95% CI: 1.057, 1.369; Pheterogeneity=0.064)." (PMID 24130810, 2013). "Additional studies are warranted to further validate ethnic difference in the effect of -607C/A polymorphisms in IL-18 gene promoter on cancer risk, especially in Africans." (PMID 24130810, 2013). "As such, and taking into consideration the previous discussion regarding IL-18’s pathogenic role in CRC, the contribution of IL-18 in tumorigenesis and the development of intestinal-specific cancer is clearly dichotomous." (PMID 23847622, 2013). "Together with the critical role of IL-18 in cancer immunity regulation, the polymorphisms of IL-18 would be related to cancer risks." (PMID 24066061, 2013). "Previously, we reported that IL-18 increased in hepatic venous blood over basal level during the sinusoidal inflammation associated with liver-infiltrating cancer cells." (PMID 21569399, 2011). "The presence of the C allele may be associated with altered IL18 expression, which is crucial for immune regulation and inflammation, both of which are vital in cancer progression." (PMID 41257666, 2025). "Both IL-18 and IL-1β are implicated in promoting the tumorigenesis of various cancers." (PMID 40338411, 2025). "IL-1β and IL-18 are highly associated with cancer progression, and IL-1β might be related to immunotherapy resistance." (PMID 39762211, 2025). "In cancer pain, key ILs implicated include IL-1, IL-6, IL-10, IL-17, IL-18, and IL-33." (PMID 38940936, 2024). "Similarly, IL‐18 is linked to poor prognosis as an immunosuppressor cytokine in cancer and is reported to be elevated in NRs to ICIs." (PMID 37681284, 2024). "When inflammasomes like NLR family pyrin domain containing 3 (NLRP3) are activated, proinflammatory cytokines like interleukin-1 beta (IL-1β) and interleukin-18 (IL-18) are secreted, which can cause a persistent inflammatory state that worsens liver damage and accelerates the growth of cancer." (PMID 38780447, 2024). "In addition, a meta-analysis has demonstrated that downregulation of IL-18 is associated with poor prognosis in carcinomas." (PMID 39451257, 2024). "One of the explanations of the limited clinical activity of IL-18 is because high levels of IL-18 are associated with impairment of NK cells, suggesting that IL-18 could have a double hedge sword effect in cancer immunotherapy." (PMID 38077389, 2023). "Some reports have linked Nnmt and IL18 with cancer progression through the STAT3/IL1β pathway." (PMID 38139000, 2023). "Both preclinical and clinical data supported that the IL-18 induction was a functionally relevant biomarker associated with the IL-10 treatment for cancer and hence it was used as a common PD endpoint that connects mice to monkeys for the efficacious dose projection." (PMID 35795558, 2022). "These highly significant findings for the AA and CA genotypes at position IL18 –607 suggest that this polymorphism may play a role in cancer progression." (PMID 35794698, 2022). "IL‐18 has been associated with pain promotion in animal models and in cancer pain patients." (PMID 35133080, 2022). "However, in some cancer polymorphisms, IL-18 correlated with protumoral effects and upregulated VEGF and SD-44 that facilitate metastasis." (PMID 34840991, 2021). "We observed that IL‐18 silencing dramatically counteracted the enhanced cell proliferation caused by elevated Pin1 expression and found IL‐18 siRNA completely counteracted the cancer‐promoting effect of Pin1." (PMID 32347623, 2020). "NLRP3 inflammasome expression may be associated with the occurrence of EMT, cancer stem cells self-renewal activation and the overexpression of IL-18, which is related to increases in myeloid-derived suppressor cells (MDSCs)." (PMID 31312615, 2019).